PDK1 (pyruvate dehydrogenase kinase 1)
Diseases named in the same sentence as PDK1 in open-access papers (continued):
Sharing a sentence is not in itself a finding about the gene and the disease.
cancer (continued). "Furthermore, other key enzymes and proteins mediating the Warburg effect, such as monocarboxylate transporter 1 and 4, hexokinase 2 (HK2), lactate dehydrogenase A (LDHA), and pyruvate dehydrogenase kinase 1 (PDK1), have also been reported to be overexpressed in different cancers." (PMID 36497394, 2022). "To validate the biological roles of 14-3-3γ in regulating PDK1/AKT signaling, we deplete endogenous 14-3-3γ in cells and reveal the potent role of 14-3-3γ in inhibiting AKT kinase by manipulating PDK1 localization and dimerization, thus promoting cancer cell malignant phenotypes." (PMID 35318320, 2022). "Similarly, the pyruvate dehydrogenase kinase 1 (PDK1) inhibitor Cpd64, when combined with EGFR TKI, improved anti-cancer effects in EGFR-mutant NCI-H1975 and NCI-H1650 cell lines and in a xenograft mouse model via the improvement of oxidative phosphorylation and mitochondrial respiration." (PMID 36532721, 2022). "In essence, these discoveries suggest that PDK1 contributes to the cancer growth and survival of BC cells, even without PI3 K oncogenic mutations, in either an AKT-dependent or AKT-independent fashion, which identifies PDK1 as a potential therapeutic target for BC." (PMID 35159078, 2022). "Through suppressing the key of enzymes of glycolysis LDHA and mitochondrial metabolism PDK1, induced by TGF-β1, the mesenchymal subtype markers N-cadherin and Vimentin are negated, suggesting that the metabolic reprogramming is directly related to cancer metastasis." (PMID 34257808, 2021). "Many PDK1-dependent AGC kinases (e.g., AKT/PKB, RSK, PKC, S6K, and SGK) are downstream effectors in the PI3K/protein kinase B (AKT) or mitogen-activated protein kinase (MAPK) growth factor signalling pathways and are aberrantly activated in various types of cancer in humans." (PMID 34879056, 2021). "Therefore, unraveling the upstream regulation of PDK1 protein turnover will likely provide insights for understanding PI3K-AKT roles in tumorigenesis, and potential targets for combating hyperactive-AKT-driven cancers." (PMID 34353330, 2021). "Interestingly, LA could coordinate with the well-known PDK1 inhibitor, dichloroacetate (DCA), which was reported inducing ROS and promote apoptosis of several cancer cells." (PMID 34211631, 2021). "Also, for cancers that do not rely on PDK1 to hold switching between glycolysis and OXPHOS, the antitumor effects of LA still need to be investigated." (PMID 34211631, 2021). "The identified link between PDK1 and IL-8 supports that the dual targeting of PDK1 (for instance, with DCA) and IL-8 (for instance, with small-molecule antagonists and humanized monoclonal antibodies) should be further studied in ovarian or other cancers as possible novel therapeutic approaches." (PMID 32071289, 2020). "Importantly, SGK3, that can be regulated through PDK1-dependent phosphorylation of residue Thr320 within its T-loop, has been identified as a key regulator of such PI3K/PDK1-dependent, Akt-independent signalling pathways in cancer." (PMID 31088502, 2019). "The results obtained from testing the two novel compounds SA16 and IB35 in cancer and non-malignant pancreatic cells suggest they could be good candidates to suppress abnormally activated molecules in both PDK1 and Aurora A signaling." (PMID 31683659, 2019). "In addition, under hypoxic conditions in the cancer microenvironment, the transcription factor hypoxia inducible factor (HIF)-1 induces GLUT1, glycolytic enzymes, and pyruvate dehydrogenase kinase-1 (PDK-1) that limit pyruvate utilization for oxidative phosphorylation and enhance aerobic glycolysis." (PMID 29954119, 2018). "In the context of sensitivity to chemotherapeutic drugs, a specific PDK1 inhibitor termed 2-O-benzyl-myo-inositol 1,3,4,5,6-pentakisphosphate (2-O-Bn-InsP5), had an additive effect in combination with rapamycin and was able to enhance the effect of paclitaxel on SKOV-3 cancer cells." (PMID 29064423, 2017).
cancer (continued). "We did not anticipate that the inhibition of PDK1 would cure cancer." (PMID 26593251, 2016). "Similarly, reduced anchorage independent growth of cancer cell following downregulation of PDK1 was not rescued by the expression of a constitutively active form of AKT." (PMID 26404259, 2015). "Besides PDK1, mTORC2 represents another kinase that might be involved in AKT-independent effects of PI3K signaling in cancer." (PMID 26404259, 2015). "Recently, miR-375 has been found to suppress core hallmarks of cancer by targeting several important genes like AEG-1, YAP1, IGF1R and PDK1.The target genes regulated by miR-375 may function spatiotemporally or in cooperation with each other in different cellular processes." (PMID 26642205, 2015). "Taken together these data suggest that, in addition to other suggested celecoxib targets such as survivin, the ER stress response and PDK1, CDH11 may play a role in mediating the COX-2 independent effects of the CelebrexTM family of anti-inflammatories in cancer and in RA." (PMID 24681547, 2014). "Taken together, these upstream signalling molecules including PI3-K, PDK-1, AKT and mTOR comprise regulatory pathways controlling cell growth, metabolism, proliferation, differentiation, motility, and survival, which attribute the overall malignancy phenotypes in human cancers." (PMID 16288304, 2005). "Thus, it is reasonable to suggest that PDK1 inhibition, singly or in combination with other PAM inhibitors, could contribute to the enhancement of antitumor efficacy in different types of human cancer." (PMID 37596643, 2023). "However, due to the lack of expression of ΔNp63 in A549 cells, whether TMEM116/PDK1 signaling pathway has effects on ΔNp63 expression in cancer development is query that has not been hitherto addressed." (PMID 34789718, 2021). "Hence, inhibition of PDK1, which is constitutively active and is capable of activating a number of AGC kinases (including Akt, S6K, SGK, PKC, PKN, and others), might ensure additional repression of cancer-relevant Akt-independent pathways in cancer cells." (PMID 28903409, 2017). "Therefore, PDK1 and PDK3 inhibition by phenylbutyrate might be therapeutically effective in cancer." (PMID 25601413, 2015). "Taken together, our results suggest that PDK1 and AGR2 are regulated by different mechanisms or that the mechanisms described for AGR2 in cancer cells do not exist in L6 myotubes." (PMID 39080182, 2024). "The reduction of the PDK1 levels can partially be explained by the DCA-stimulated degradation of HIF-1α in cancer cells, while HIF-1α does not seem to play a role in reducing the PDK1 protein levels in L6 myotubes." (PMID 34445316, 2021). "Unlike the oncogenic roles of PDK1-3 in multiple human cancers, the findings from this study and those from other labs have illustrated that PDK4 plays a divergent role in various cancers, depending on different cell contexts." (PMID 32489458, 2020). "The results of this study were consistent with these findings, as NAC1-overexpressed cancer cells would result in the accumulation of pyruvate in hypoxia, and NAC1 can induce PDK3 but not PDK-1, -2, or -4 expression in hypoxia." (PMID 29163184, 2017). "The findings suggest that the unintended activation of the PDK1/Akt/mTOR may be one reason why a potent PTKI such as ponatinb, despite its potent inhibition of its intended targets, may not work well against some cancers." (PMID 30959969, 2019). "As many PIK3CA mutant cancers rely on effectors other than AKT, such as PDK1 and its substrate SGK3, phospho-AKT may not be an ideal pharmacodynamic biomarker for relevant PI3K inhibition." (PMID 27465249, 2016). "In addition, we assumed that these metabolic changes were predominant in cancer cell lines because HEK-293, a non-cancerous cell line, demonstrated little metabolic change despite high PDK-1 expression." (PMID 23135628, 2013).
infection (29 papers, 2011 to 2025). The state of being infected such as from the introduction of a foreign agent such as serum, vaccine, antigenic substance or organism. "The majority of the glycolysis genes showed a significant decline in transcription after infection, but at the same time, the expression of genes that regulate key enzymes like Pfkfb3 and Pdk1 in glycolysis were upregulated." (PMID 38992966, 2025). "There were only two exceptions: 1) the infection with C. burnetii induced a significantly higher expression of PKM2 under hypoxia than LPS; 2) the infection with C. burnetii induced a significantly higher expression of PDK1 under normoxia than LPS." (PMID 35755850, 2022). "Infection of intestinal organoids with this glycolytic reporter revealed a compartmentalization of Pdk1 expression, with only few cells expressing the mCherry reporter." (PMID 35314684, 2022). "Here we reported PDK1 intrinsically promotes the Tfh cell differentiation and germinal center responses upon acute infection by using conditional knockout mice." (PMID 33595435, 2021). "We infected wild-type C57BL/6J mice with LCMV Armstrong strain and observed elevated expression level of PDK1 in Tfh cells compared with naïve CD4+ T or Th1 cells on day 8 post-infection (8 dpi), which suggested potential roles of PDK1 in Tfh cells." (PMID 33595435, 2021). "Further investigation revealed that among the four PDK subtypes, only PDK-1 mRNA was upregulated by NDV infection (24 h post infection), suggesting the importance of PDK-1 in NDV-induced high-rate glycolysis." (PMID 31819179, 2020). "Consistently, under hypoxia, the infection of the wild-type EPEC E2348/69 strain induced the expressions of PDK1, PGK1, SLC2A1 (GLUT1), and PKM2, four well-defined HIF-1α targets, but did not induce the expression of SOD2, a well-defined HIF-2α target." (PMID 30125331, 2018). "When HIF-1α was knocked-down by adding HIF-1α-shRNA-2 lentivirus, the enhancement of expression of SLC2A1 (GLUT1) and PDK1 by infection with the wild-type EPEC E2348/69 strain was diminished." (PMID 30125331, 2018). "MVM-infected A9 cells display changes in PDK1/PKC/PKB signaling that are essential to promoting a productive infection." (PMID 25742010, 2015). "In the first hours of infection (2 and 6 hours), live parasites induce a significant increase of Pfk, Pdk1, Pkm2 and Ldha transcripts as compared to either uninfected cells or challenged with irradiated promastigotes." (PMID 25738568, 2015). "Studies have shown that angiotension-II-induced focal adhesion formation is inhibited by infection with Adeno-PDK1-Y9F via paxillin." (PMID 26684827, 2015). "Together, these results suggest that a host factor mediates PDK-1 dephosphorylation in response to infection with H. pylori." (PMID 26487493, 2015). "Having shown that Salmonella-induced phosphorylation of Akt is dependent on PDK1 and rictor we next sought to confirm that these kinases are translocated to the plasma membrane during infection." (PMID 21779406, 2011). "Furthermore, with respect to infection duration, the PDK1, AMPK and MCT1 levels have changed significantly at p < 0.001, while UCP2 and PDH levels have changed significantly at p < 0.01." (PMID 33093503, 2020). "Amplified HIF-1α caused upregulation of GLUT-1 and PDK1 in controls that was not further enhanced by infection." (PMID 31036602, 2019). "However, total level of PDK1 and Akt remained constant upon infection." (PMID 27494323, 2016). "Such an effect was confirmed in PA infection, where PA-derived DnaK negatively regulates IL-1β production by cross-talk between JNK and PI3K/PDK1/FoxO1 pathways." (PMID 41164165, 2025). "The infection with wild-type and ΔdotA C. burnetii increases the expression of PKM2 and LDHA in normoxic and hypoxic BMDM, and the expression of Glut1 and PDK1 only in normoxic BMDM." (PMID 35755850, 2022).
infection (continued). "During the four days following the infection, with respect to MOI, the UCP2, PDH and AMPK levels have changed significantly at p < 0.001, while MCT1 and PDK1 levels have changed significantly at p < 0.05." (PMID 33093503, 2020). "Both Akt1 and Akt2 were demonstrated to phosphorylate PDK1, and PDK4 expression was markedly inhibited by infection with shRNA directed against Akt1." (PMID 31398213, 2019). "Additionally, infection with N. caninum tachyzoites promoted HK2, LDH-A, and PDK1 protein levels while increasing glucose consumption and lactate production in the in vivo and in vitro models." (PMID 40307939, 2025). "Interestingly, we observed a greater increase in phosphorylation at T308 than S473 during lytic infection which suggests that HCMV miRNAs preferentially regulate pathways leading to T308 phosphorylation mediated by PDK1." (PMID 39661658, 2024). "Moreover, PX-478 prevented the enhanced expressions of SLC2A1 (GLUT1), PDK1, and PKM2 induced by infection with the mutant EPEC strain ΔnleBE+pNleB." (PMID 30125331, 2018). "In agreement, amastigote infection failed to upregulate the mRNA levels of glycolytic enzymes as compared with uninfected macrophages, with the exception of Pdk1, a regulator of the activity of the pyruvate dehydrogenase complex." (PMID 25738568, 2015). "Interestingly, substitution of glutamic acid for this residue renders PDK1 constitutively active as regards PKB activation, and phosphorylation at this site is specifically triggered upon MVM infection." (PMID 25742010, 2015). "The PDK1 was also undetected in SopF:His immunoprecipitated samples both at early and late stages of infection, suggesting that SopF could not directly interact with PDK1." (PMID 36803521, 2023). "Notably, HIF-1α is important for neutrophil survival in normoxia as well as hypoxia, and VEGFA and many other HIF-1α target genes, but not HIF1A itself, are upregulated following LVS infection including HK2, LDHA, PDK1 and SCL2A1." (PMID 35873156, 2022). "The infection with a recombinant virus lacking the C16 protein resulted in the decreased transcription of HIF-1α-responsive genes, such as vascular endothelial growth factor (VEGF), pyruvate dehydrogenase kinase 1 (PDK-1), and GLUT-1, which are important regulators of cellular metabolism." (PMID 34517756, 2021).
adenocarcinoma (7 papers, 2006 to 2025). A common cancer characterized by the presence of malignant glandular cells. "HC analysis indicated that adenocarcinomas induced in MMTV-PDK1 mice expressed elevated levels of PDK1, pT308AKT and PPARδ in comparison to histologically matched tumors from wild-type mice." (PMID 21297860, 2011). "Mammary fat pad isografts of PDK1-expressing cells produced invasive adenocarcinomas." (PMID 16551362, 2006). "Comma/PDK1 cells grew into invasive and vascular poorly differentiated adenocarcinomas within 8 weeks after transplantation, in contrast to the normal mammary gland morphology produced by control cells." (PMID 16551362, 2006).
metabolic disease (5 papers, 2023 to 2025). A congenital disorder (due to inherited enzyme abnormality) or acquired (due to failure of a metabolically important organ) disorder resulting from an abnormal metabolic process. "In conclusion, we confirmed that PDK1 inhibitor exacerbated the development of OA, and the underlying mechanism might be related to the glucose metabolism disorder, which leads to an imbalance of anabolic and catabolic processes of chondrocytes and accelerates inflammation." (PMID 37474941, 2023). "Recent evidence reveals that regulation of adipocyte FoxO1 by 3′-phosphoinositide-dependent kinase 1 (PDK1) plays an important role in metabolic disease." (PMID 37941908, 2023). "Here, we identify a potential role for aberrant protein phosphorylation due to low expression of PDK1 that may further contribute to metabolic disease phenotypes characteristic of the NZO mouse." (PMID 36944993, 2023).
neurological disease (3 papers, 2017 to 2025). "PDK1 is a key member in the PI3K signaling and has been implicated in neurological diseases." (PMID 29104535, 2017). "However, the effect of PDK1 in diabetic hyperglycemia-induced neurological disease is ignored." (PMID 37935660, 2023).
cardiac disease (2 papers, 2017 to 2025). "It has been well established that PDK1 activates Akt/mTOR signaling in severe cardiac disease." (PMID 28536634, 2017). "Although proteomics studies of diseased hearts found no changes in PDK1 protein abundance, a recent phosphoproteomics study of diabetic and ischemic cardiomyopathic patients revealed decreased phosphorylation of the PDK1-specific serine 232 site on PDH, further implicating PDK1 in cardiac disease." (PMID 40074083, 2025).
benign tumours (1 paper, 2008). "Four out of 10 benign tumours showed negative PDK1 staining, whereas weak cytoplasmic staining was evident in 5 out of 10 benign tumours." (PMID 18349831, 2008).
neurodegenerative disease (1 paper, 2017). A disorder of the central nervous system characterized by gradual and progressive loss of neural tissue and neurologic function. "Recent evidence has shown that PDK1 is involved in neurodegenerative disease, but how it exerts its role is controversial." (PMID 29104535, 2017). "Decreased expression but increased activity of PDK1 has been observed in neurodegenerative disease." (PMID 29104535, 2017).
PDK1 also shares sentences with these, for which no sentence is quoted: breast (3 papers); pancreatic ductal adenocarcinoma (3); chordoma (2); depression (2); Hepatic steatosis (2); Impaired glucose tolerance (2); kidney disease (2); prostate tumors (2); pulmonary arterial hypertension (2); rheumatoid arthritis (2); Alexander disease (1); and-neck carcinoma (1); ankylosing spondylitis (1); Arthritis (1); Atrophy (1); benign cystadenomas (1); brain cancer (1); chlamydial infection (1); chronic rhinosinusitis (1); cognitive disorder (1); colon adenocarcinoma (1); Crohn disease (1); developmental delay (1); digestive system tumors (1); Energy (1); experimental autoimmune encephalomyelitis (1); fibrosarcoma (1); Friedreich ataxia (1); gastric diseases (1); glomerulosclerosis (1).
A further 34 diseases each share a sentence with PDK1 in 1 paper.